SNORD81 (Small nucleolar RNA SNORD81 )
Synonyms: LOC124900235
Gene: Small nucleolar RNA gene on chromosome 7 (137,287,687 to 137,287,762, forward strand). Ensembl gene ENSG00000202023.
Gene Ontology:
Biological process: RNA processing
Cellular component: nucleolus
Homologues: Orthologues: chimpanzee SNORD81 (99% identical), macaque SNORD81 (97% identical), mouse Gm25789 (88% identical), rabbit SNORD81 (88% identical), rat Snord81 (88% identical), mouse Gm25802 (86% identical), pig SNORD81 (84% identical), guinea pig SNORD81 (79% identical), guinea pig SNORD81 (71% identical). Paralogues in human: SNORD81 (87% identical), SNORD81 (71% identical).